RNU6-1157P (RNA, U6 small nuclear 1157, pseudogene)
Gene: Small nuclear RNA gene on chromosome 11 (118,593,988 to 118,594,093, forward strand). Ensembl gene ENSG00000207185.
Homologues: Orthologues: chimpanzee U6 (99% identical), macaque U6 (91% identical), dog U6 (81% identical). Paralogues in human: RNU6-1145P (86% identical), RNU6-16P (86% identical), RNU6-41P (86% identical), RNU6-820P (86% identical), RNU6-208P (85% identical), RNU6-38P (85% identical), RNU6-393P (85% identical), RNU6-45P (85% identical), RNU6-1083P (84% identical), RNU6-10P (84% identical), RNU6-12P (84% identical), RNU6-13P (84% identical), and 1285 more.